PHLDA1 (pleckstrin homology like domain family A member 1)
Description:
Seems to be involved in regulation of apoptosis. May be involved in detachment-mediated programmed cell death. May mediate apoptosis during neuronal development. May be involved in regulation of anti-apoptotic effects of IGF1. May be involved in translational regulation.
Synonyms: PHRIP; TDAG51; DT1P1B11
Tractability: PROTAC: ubiquitination databases record sites on it.
Gene: Protein-coding gene on chromosome 12 (76,025,447 to 76,031,776, reverse strand). Ensembl gene ENSG00000139289.
Subcellular location: Cytoplasm; Cytoplasmic vesicle; Nucleus, nucleolus
Subcellular location (Human Protein Atlas): Nucleoli; Nucleoli rim; Nucleoplasm
Pathways (Reactome):
Cell Cycle: Interaction between PHLDA1 and AURKA
Gene expression (Transcription): MLL4 and MLL3 complexes regulate expression of PPARG target genes in adipogenesis and hepatic steatosis
Gene Ontology:
Molecular function: protein binding; phosphatidylinositol phosphate binding
Biological process: positive regulation of apoptotic process
Cellular component: cytoplasm; cytoplasmic vesicle; nucleolus; cytosol; nucleus
Genetic constraint (gnomAD): Loss-of-function variants: 23 observed, 23.12 expected, observed/expected ratio (o/e) 0.99, 90% interval 0.71 to 1.41. The synonymous counts are far from expectation, so gnomAD's model fits this gene poorly and the ratio says little. Missense variants: 479 observed, 405.98 expected, observed/expected ratio (o/e) 1.18, 90% interval 1.09 to 1.27. Synonymous variants: 221 observed, 176.24 expected, observed/expected ratio (o/e) 1.25, 90% interval 1.12 to 1.4.
Homologues: Orthologues: chimpanzee PHLDA1 (99% identical), mouse Phlda1 (86% identical), rat Phlda1 (85% identical), guinea pig PHLDA1 (84% identical), rabbit PHLDA1 (82% identical), macaque PHLDA1 (64% identical), pig PHLDA1 (55% identical), dog PHLDA1 (34% identical), tropical clawed frog phlda1 (33% identical), zebrafish phlda1 (25% identical). Paralogues in human: PHLDA3 (16% identical), PHLDA2 (15% identical).
Diseases named in the same sentence as PHLDA1 in open-access papers:
PHLDA1 is named in the same sentence as 100 diseases in open-access papers, as found by Europe PMC text mining. Sharing a sentence is not in itself a finding about the gene and the disease. The quoted sentences say what the papers report.
breast carcinoma (22 papers, 2008 to 2025). "Decreased expression of PHLDA1 is associated with decreased overall survival in patients with breast cancer, gastric adenocarcinoma, or non-small cell lung cancer." (PMID 41430389, 2025). "The downregulation of PHLDA1 and estrogen receptor expression in breast cancers have also been linked." (PMID 38921000, 2024). "It was revealed that PHLDA1 mRNA expression was higher, which leads to a higher risk of distant metastasis in estrogen receptor (ER)-positive breast cancers, but PHLDA1 exerts the opposite effects on breast cancers that are ER-negative." (PMID 38921000, 2024). "Downregulation of PHLDA1 was associated with poor prognosis, more advanced clinical stage, and decreased overall survival (OS), as shown by the analysis of Kaplan–Meier curves in breast cancer patients." (PMID 39630301, 2025). "Additionally, the overexpression of PHLDA1 enhanced cells sensitivity to lapatinib, and caused 50% inhibition of colony formation in breast cancer." (PMID 39630301, 2025). "Another study showed that PHLDA1 negatively controls cell differentiation in the MCF-7 breast cancer cells by inhibiting heregulin-dependent ErbB3 receptor activation." (PMID 39630301, 2025). "Noteworthy, PHLDA1 was identified as an important negative regulator of aurora A kinase in breast cancer as it contributes to the degradation of this oncoprotein." (PMID 39630301, 2025). "In a report concerning breast cancer, the upregulation of PHLDA1 in HME16C mammary epithelial cells inhibited ERK-mediated transformation." (PMID 39630301, 2025). "In conclusion, the oncosuppresor functions of PHLDA1 are broadly documented in a variety of tumors such as breast cancer, neuroblastoma, cholangiocarcinoma, gastric adenocarcinoma, or melanoma." (PMID 39630301, 2025). "As a matter of fact, PHLDA1 was found to be up-regulated in both autophagy and apoptosis induced by rapamycin in T-47D breast carcinoma." (PMID 39630301, 2025). "Reduced PHLDA1 expression is seen in melanoma, breast carcinoma, oral carcinoma, and gastric adenocarcinoma, while upregulation was reported in colon cancer and in human intestinal adenoma and carcinoma." (PMID 39334449, 2024). "On the other hand, PHLDA1 expression is also a significant indicator of poor prognoses in breast cancer patients." (PMID 38921000, 2024). "Reduced PHLDA1 expression has been observed in gastric adenocarcinoma, breast carcinoma, oral carcinoma, and melanoma." (PMID 38921000, 2024). "For example, an analysis of the GEO dataset using the prognostic database showed the overall survival of a patient with breast cancer and lung cancer in relation to PHLDA1 gene expression." (PMID 38921000, 2024). "Here, we present a novel strategy to circumvent lapatinib resistance in HER2+ breast cancer by using a clinically relevant HDAC inhibitor to restore PHLDA1 expression." (PMID 37047202, 2023). "Restoring PHLDA1 expression therefore represents an attractive prospect for circumventing drug resistance in RTK-driven cancers such as HER2+ breast cancer." (PMID 37047202, 2023). "The precise mechanism through which PHLDA1 induction restores sensitivity to lapatinib in HER2+ breast cancer models requires further investigation." (PMID 37047202, 2023). "In line with this, we show that treatment with the clinically relevant class I histone deacetylase (HDAC) inhibitor 4SC-202 restores PHLDA1 expression in lapatinib-resistant human epidermal growth factor receptor-2 (HER2)+ breast cancer cells." (PMID 37047202, 2023). "In the present study, using an inhibitor-based approach, we identified a PKC/MAPK-mediated mechanism of PHLDA1 regulation in HER2+ breast cancer cell lines." (PMID 37047202, 2023). "We have shown that the recovery of PHLDA1 levels, using a doxycycline-inducible expression construct, restores the sensitivity of drug-resistant breast cancer cell lines to targeted therapy." (PMID 37047202, 2023).
breast carcinoma (continued). "We have shown that PHLDA1 expression is downregulated in lapatinib-resistant HER2+ breast cancer cells and can be depleted in parental cell populations by treatment with lapatinib for 24 h." (PMID 37047202, 2023). "The regulation of endogenous PHLDA1 expression in HER2+ breast cancer cells is therefore likely to be controlled largely by PKC/MAPK signalling, consistent with observations in immortalised human mammary epithelial cells and MEK1 mutant cancers." (PMID 37047202, 2023). "Accordingly, the treatment of lapatinib-resistant breast cancer cell lines with 4SC-202 led to an increase in PHLDA1 levels and elevated H3K27ac at the PHLDA1 locus." (PMID 37047202, 2023). "We have shown that treatment of HER2+ breast cancer cell lines with lapatinib leads to the downregulation of PHLDA1." (PMID 37047202, 2023). "Mechanistically, we demonstrated that ER and NFĸB work together to regulate a feedback loop involving the downregulation of miR-181 and the upregulation of its target, PHLDA1, to enhance stem properties in ER+ breast cancer cell lines." (PMID 36482488, 2022). "In melanoma, breast cancer, oral cancer, and stomach cancers, the reduced expression of PHLDA1 has already been described." (PMID 36092920, 2022). "Previously, we identified that AURKA directly phosphorylates and degrades PHLDA1 in breast cancer cells." (PMID 34625072, 2021). "In breast cancer, PHLDA1 was identified as a strong inhibitor of the metastasis capability of breast cancer cells through regulating Aurora A deregulation, indicating that PHLDA1 functions as a suppressor of breast cancer." (PMID 32983961, 2020). "PHLDA1 levels were reduced significantly in the HER2+ breast cancer cell line, MCF7/HER2-18, following exposure to trastuzumab." (PMID 29490281, 2018). "PHLDA1 loss is able to confer resistance to trastuzumab in both in vitro and in vivo models of HER2+ breast cancer." (PMID 29490281, 2018). "In estrogen receptor (ER) positive breast cancer, ER and NF-κB worked together to upregulate PHLDA1 expression directly through enhanced transcription and indirectly through repression of miR-181a and miR-181b." (PMID 30410722, 2018). "We find significant down-regulation of PHLDA1 in primary breast cancer and PHLDA1 is statistically significantly less expressed in ErbB2 negative compared with ErbB2 positive tumors consistent with its regulation by ErbB2." (PMID 25238247, 2014). "PHLDA1 expression was significantly reduced in human breast cancer tissue versus adjacent normal mammary epithelium (p<0.05)." (PMID 25238247, 2014). "In order to further dissect the role of PHLDA1 in breast cancer cells, PHLDA1 expression constructs were generated and expression of PHLDA1 was confirmed by detection of the hemagglutinin tag." (PMID 25238247, 2014). "So PHLDA1 can fine-tune the overall output of ErbB2 signaling in ErbB2 dependent lung and breast cancer cells." (PMID 25238247, 2014). "A closer look at the eight Ox-E/ER genes linked to these growth factors revealed that most (EGR1, PHLDA1, IGFBP5, TAGLN, DAB2, and FHL2) have been associated with breast cancer." (PMID 18631401, 2008). "Therefore, it was concluded that PHLDA1 is upregulated directly by estrogen receptor/NFkB signalling and indirectly by inhibiting miR-181 and these events promote breast cancer progression." (PMID 39630301, 2025). "PHLDA1 downregulation predicts poor prognosis in breast cancer, especially in ER-negative patients." (PMID 40340807, 2025). "PHLDA1 is a potential prognostic marker of patient survival in breast cancer." (PMID 39630301, 2025). "On the other hand, PHLDA1 downregulation was shown to induce chemoresistance of breast cancer." (PMID 38495105, 2024). "This suggests that PHLDA1, depending on the estrogen receptor status, which affects the clinical behavior of tumors, may play various roles in breast cancer cells." (PMID 38921000, 2024).
breast carcinoma (continued). "Reduced PHLDA1 expression promotes the development of breast cancer and may be an effective prognostic indicator of prognosis." (PMID 38921000, 2024). "Nevertheless, in breast cancer, PHLDA1 could negatively regulate Aurora A and antagonize Aurora A-mediated oncogenic pathways, and decreased PHLDA1 expression was associated with poorer prognosis." (PMID 39033192, 2024). "We therefore sought to investigate whether the inhibition of HDAC2, HDAC4, or KDM1A would restore the expression of PHLDA1 in lapatinib-resistant HER2+ breast cancer cells." (PMID 37047202, 2023). "The PHLDA1 gene was found to be up-regulated in both autophagy and apoptosis processes induced by rapamycin and silencing of this gene resulted in a reduction of these activities in T-47D breast carcinoma cells." (PMID 30027525, 2018). "Down-regulation of PHLDA1 protein was found in breast cancer and patients with low PHLDA1 protein levels had shorter disease-free survival and overall survival than patients with high PHLDA1 protein levels, which suggested that it was a strong predictor of poor prognosis for breast cancer patients." (PMID 30410722, 2018). "Indeed, induction of PHLDA1 expression in both endometrial and breast cancer models resulted in a marked decrease in Akt phosphorylation." (PMID 29490281, 2018). "Moreover, as with our endometrial cancer cell lines, re-expression of PHLDA1 re-sensitizes lapatinib-resistant HER2+ breast cancer cells." (PMID 29490281, 2018). "In addition, our in vivo study showed a modest but significant down-regulation of PHLDA1 in primary breast cancer, which is consistent with previously reported findings." (PMID 25238247, 2014). "Thus, we showed that PHLDA1 upregulation inhibits cell proliferation under attached, as well as anchorage-independent conditions in breast cancer cells." (PMID 25238247, 2014). "In limited studies, PHLDA1 has been reported to be highly expressed in pancreatic cancers as well as human intestinal tumors, while downregulation of PHLDA1 was noted during melanoma as well as breast cancer progression." (PMID 25238247, 2014). "Our findings suggest that PHLDA1 might have key inhibitory functions in ErbB2 driven lung and breast cancer cells and a better understanding of its functions might point at novel therapeutic options." (PMID 25238247, 2014). "Additionally, a significant downregulation of PHLDA1 in primary human breast cancer was found by immunohistochemical staining and PHLDA1 was significantly less expressed in ErbB2-negative tumors as compared with ErbB2-positive tumors, where PHLDA1 was expressed abundantly." (PMID 39630301, 2025). "However, it was unclear how PHLDA1 expression correlated with breast cancer survival." (PMID 38921000, 2024). "In addition, reduced expression of PHLDA1 could enhance proliferate and migration of breast cancer cells and was related to unfavorable prognosis." (PMID 34434692, 2021). "The PHLDA1 gene was reported to be up-regulated in both autophagy and apoptosis and silencing of this gene was found to reduce both activities, strongly suggesting that PHLDA1 mediates and positively regulates both autophagy and apoptosis pathways in T-47D breast carcinoma cells." (PMID 30027525, 2018). "In another study, PHLDA1 upregulation inhibited cell proliferation and motility, as shown by reducing chemotaxis in MDA-MB-231 breast cancer cells." (PMID 39630301, 2025). "The inhibition of HDAC by 4SC-202 restored the PHLDA1 expression in lapatinib-resistant SKBR3 and HCC1954 breast cancer cells." (PMID 39630301, 2025). "First, PHLDA1 can bind and negatively regulate the mitotic aurora A kinase in MDA-MB-231 breast cancer cells." (PMID 41430389, 2025). "The group also showed that treating SKBR3 and HCC1954 breast cancer cells with lapatinib (inhibitor of EGFR/ErbB1 and ErbB2) led to a decrease in PHLDA1 as assessed by immunoblotting." (PMID 39630301, 2025).
breast carcinoma (continued). "Accordingly, matrix-embedded spheroids of the HER2+ breast cancer cell line HCC1954 exhibited growth arrest following treatment with lapatinib, which was diminished with PHLDA1 knockdown." (PMID 37047202, 2023). "PHLDA1, a gene homologous to PHLDA2, inhibits autophagy in neuroblastoma and promotes autophagy in breast cancer cells." (PMID 32385195, 2020). "In support of this, we determined the importance of PHLDA1 expression in parental and lapatinib-resistant populations of two further HER2+ breast cancer cell lines, SKBR3 and HCC1954." (PMID 29490281, 2018). "Since treatment with phorbol 12-myristate 13-acetate (PMA) stimulated the PHLDA1 expression in human T-cells, we investigated whether PMA treatment could reverse PHLDA1 downregulation in drug-resistant breast cancer cells." (PMID 37047202, 2023). "PHLDA1, a homologous gene of TSSC3 (PHLDA2) has been reported to regulate autophagy in breast cancer and neuroblastoma cells, which also suggested that TSSC3 might have the ability to regulate autophagy." (PMID 30092789, 2018). "We demonstrate broad clinical relevance of our findings, showing that PHLDA1 downregulation also occurs in response to RTK-targeted therapy in breast and renal cancer patients, as well as following trastuzumab treatment in HER2+ breast cancer cells." (PMID 29490281, 2018). "We speculate that PHLDA1 might have key inhibitory functions in EGFR and ErbB2-driven lung and breast cancer cells and a better understanding of its functions might point at novel therapeutic options through modulation of this important negative feedback loop." (PMID 25238247, 2014). "We also found that PHLDA1 is significantly less expressed in ErbB2 negative tumors compared with the ErbB2 positive breast cancers." (PMID 25238247, 2014). "Expression of PHLDA1 mRNA and TDAG51 protein in breast cancer has recently been described." (PMID 18597688, 2008). "We previously identified that the downregulation of Pleckstrin Homology-Like Domain family A member 1 (PHLDA1) underpins resistance to receptor tyrosine kinase (RTK)-targeted therapy in both fibroblast growth factor receptor 2 (FGFR2)-mutant endometrial and HER2-amplified breast cancers." (PMID 37047202, 2023). "Furthermore, we examined whether a highly transcriptionally regulated ERK pathway target, PHLDA1 (TDAG51), suggested to be a tumor suppressor in breast cancer and melanoma, might modulate the transformation process." (PMID 18597688, 2008). "PHLDA1 may be down-regulated in breast cancer with ER negative." (PMID 30410722, 2018).